SFTA3 (surfactant associated 3)
Description:
Putative surfactant protein. May be involved in wound healing and in the reduction of the surface tension at the ocular surface.
Synonyms: SP-H; NANCI; PAHRF; formerly SFTPH
Gene: Long non-coding RNA gene on chromosome 14 (36,473,288 to 36,513,873, reverse strand). Ensembl gene ENSG00000229415.
Subcellular location: Cytoplasm; Secreted
Pathways (Reactome):
Disease: Defective CSF2RA causes SMDP4; Defective CSF2RB causes SMDP5
Metabolism of proteins: Surfactant metabolism
Diseases named in the same sentence as SFTA3 in open-access papers:
SFTA3 is named in the same sentence as 11 diseases in open-access papers, as found by Europe PMC text mining. Sharing a sentence is not in itself a finding about the gene and the disease. The quoted sentences say what the papers report.
lung adenocarcinoma (3 papers, 2021 to 2024). A carcinoma that arises from the lung and is characterized by the presence of malignant glandular epithelial cells. "Notably, the expression of lung adenocarcinoma marker genes such as SFTA2 and SFTA3 was widespread and almost completely lost in cancer cells of T790M− tumors." (PMID 36092941, 2022). "Similarly, this DCB subtype specificity also extends to lung cancer: 4 of the 6 lung DCB genes (CXCL17, SFTA3, SFTPA2, and SLC34A2) were upregulated in the plasma of patients with lung adenocarcinoma compared to those with squamous cell carcinoma." (PMID 33883548, 2021).
lung carcinoma (3 papers, 2021 to 2024). "SFTA3 was identified as a novel immune-activating protein in lung cancer, and it is also thought to be associated with phase M." (PMID 35954390, 2022). "Among the lung cancer DCB genes, many are associated with surfactant proteins (e.g., SFTA3, SFTPA2, SLC34A2, and BPIFA1), which function to lower surface tension at the air/liquid interface in alveolar cells." (PMID 33883548, 2021). "In this study, 6 hub genes,NKX2-1,CD8A,SFTA3,IL2RB,IDO1, andCXCL9, which are all M1 macrophage coexpressed genes, were utilized to build the immunotherapy response model.NKX2-1 can regulate lung cancer growth by targeting the MAPK pathway." (PMID 38379417, 2024).
anaplastic thyroid carcinoma (1 paper, 2017). "SFTA3 is also downregulated in anaplastic thyroid carcinoma compared with normal thyroid tissue." (PMID 29069744, 2017).
Central hypothyroidism (1 paper, 2021). A type of hypothyroidism due to an insufficient stimulation of an otherwise normal thyroid gland. "Similarly, IGSF1 (leads to central hypothyroidism), SFTA3 and GLIS3, whose mutations are linked to CH, were identified." (PMID 34249923, 2021).
hypothyroidism (1 paper, 2021). Abnormally low levels of thyroid hormone. "Thirdly, SFTA3, a surfactant protein which is overexpressed both in adult and fetal thyroids, was recently found to be mutated in patients presenting hypothyroidism." (PMID 34249923, 2021).
cancer (4 papers, 2017 to 2025). A tumor composed of atypical neoplastic, often pleomorphic cells that invade other tissues. "Six genes—HFE2, LOC339674, SERINC2, SFTA3, SOX2OT, and ACPP—emerged as the most promising candidates, supported by enrichment and survival associations across multiple cancers." (PMID 41408184, 2025). "Additionally, the expression of the lung cancer associated transcription factor, NKX2-1, is highly correlated with its methylation and also clusters with several other lung- associated genes, for example, SFTA3 and SOX2, at the PTM level." (PMID 28994825, 2017).
adenocarcinoma (1 paper, 2025). A common cancer characterized by the presence of malignant glandular cells. "They observed pervasive transcriptional downregulation of adenocarcinoma lineage markers (NAPSA, NKX2-1, SFTA2, and SFTA3), validated orthogonally via multiplex immunohistochemistry." (PMID 41516316, 2025).
bacterial infection (1 paper, 2018). "As it is known that DED is accompanied by inflammation and sometimes bacterial infection, these pathologic states may cause an increased expression of SFTA3." (PMID 29955092, 2018).
tumour (1 paper, 2017). "The rs944289 showed a greater significant association with NKX2-1 and SFTA3 expression levels compared with rs34081947 in both the tumour and normal tissues." (PMID 28703219, 2017).
SFTA3 also shares sentences with these, for which no sentence is quoted: squamous cell carcinoma (3 papers); breast carcinoma (1).